NES (nestin)
Diseases named in the same sentence as NES in open-access papers (continued):
Sharing a sentence is not in itself a finding about the gene and the disease.
Hyperglycemia (5 papers, 2012 to 2021). An increased concentration of glucose in the blood. "After 5 days, however, hyperglycemia increased, whereas coculture with M1 macrophages reduced Nestin mRNA levels." (PMID 34064969, 2021). "In contrast, in H6c7-kras cells, Nestin mRNA levels were elevated by M1 macrophages and hyperglycemia at both times points." (PMID 34064969, 2021). "MRNA levels of the CSC marker Nestin were clearly induced by short-term exposure to M1 macrophages and slightly amplified by hyperglycemia." (PMID 34064969, 2021). "By contrast, endothelial cell density was decreased by hyperglycemia, as assessed after either nestin immunohistochemistry or in situ hybridization with the mouse-specific VEGFR2 probe." (PMID 22272235, 2012). "Reactive gliosis represents the response of Müller cells to hyperglycemia, a process characterized by a specific pathophysiological mechanism: hypertrophy, cellular proliferation, and increased intermediate filament proteins nestin, vimentin and glial fibrillary acidic protein (GFAP)." (PMID 28238189, 2017). "Moreover, the downregulation of nestin protein levels in VSMCs of STZ-induced diabetic rats was attributed in part to hyperglycemia as exposure of 1st/2nd passage carotid artery and aortic VSMCs to 30 mM D-glucose significantly reduced expression, whereas lineage specific markers were unaffected." (PMID 25139503, 2014). "Overall, these data indicate that PDEC undergo changes in the expression of CSC marker genes (mainly of Nestin) when exposed to M1 macrophages and hyperglycemia but that this does not result in an enhanced self-renewal capacity or elevated colony formation ability." (PMID 34064969, 2021).
leukemia (5 papers, 2020 to 2025). A malignant (clonal) hematologic disorder, involving hematopoietic stem cells and characterized by the presence of primitive or atypical myeloid or lymphoid cells in the bone marrow and the blood. "Notably, the co-expression of nestin and P-gp has been reported in both human neural stem/progenitor cells and multidrug resistance variants of leukemia cells, indicating a potential role for nestin in regulating P-gp expression and function." (PMID 40429842, 2025). "Nestin, a type VI intermediate filament protein, is typically expressed in neural stem cells, but has also been found in cancer cells, including leukemia." (PMID 40429842, 2025). "The co-expression of P-gp with other proteins, such as nestin, has been observed in leukemia cell lines." (PMID 40429842, 2025). "Sympathetic nerve cells maintain BM Schwann cells and nestin+ cells, whereas leukemia progression is facilitated by a reduction in nerve fibers, which results in the apoptosis of nestin+ MSCs and a subsequent drop in CXCL12 levels." (PMID 38169927, 2023). "In contrast, in vivo nestin+ cell depletion in primary AML mice significantly decreased leukemia burden and extended mouse survival." (PMID 32966766, 2020). "Doxycycline was administered after 2 weeks to induce AML, and nestin+ cells were depleted by tamoxifen administration upon leukemia development, i.e., once peripheric blood showed high WBC (see STAR Methods), around 5 weeks later." (PMID 32966766, 2020). "This study shows that BMSCs expressing the marker nestin directly support leukemia stem cell (LSC) survival and chemoresistance." (PMID 32966766, 2020). "In an MLL-AF9 AML model, the leukemia development causes local neuropathy, reducing the number of NG2+ periarteriolar cells, which are involved in the maintenance of HSC quiescence, and leading to the osteogenic differentiation of Nestin+ MSCs." (PMID 37234820, 2023). "Moreover, nestin+ cell depletion in chimeric mice carrying AML cells and WT cells did not affect normal hematopoietic progenitors but selectively decreased leukemia burden." (PMID 32966766, 2020).
lung adenocarcinoma (5 papers, 2018 to 2021). A carcinoma that arises from the lung and is characterized by the presence of malignant glandular epithelial cells. "Immunocytochemical staining of the respective CSC markers in the well-established lung adenocarcinoma-derived cell line LXF-289 revealed no expression for cancer stem cell markers CD133 and Nestin and only low expression of CD44 in comparison to LCSC-like cells." (PMID 33925297, 2021). "Additionally, immunocytochemical investigation of the well-established lung adenocarcinoma cell line LXF-289 revealed no expression for CD133 and Nestin and lower expression of CD44, underpinning the presence of a CSC phenotype in the here-presented BKZ cell populations." (PMID 33925297, 2021).
metastatic melanoma (5 papers, 2013 to 2024). A melanoma that has spread from its primary site to another anatomic site. "When analyzing differential expression using GEPIA2, we have found a significantly higher expression for LOXL3 and NES in cutaneous metastatic melanoma, both in BRAF+ and BRAF– tumors, compared to normal skin samples." (PMID 39273022, 2024). "Nestin was the only marker demonstrating a statistical difference when comparing primary and metastatic melanoma (p = 0.05), with all cases of metastatic melanoma expressing at least one stem cell marker." (PMID 27429260, 2014). "Primary and metastatic melanoma tissue expressed higher levels of CD166 (p = 0.005), CD133 (p = 0.003), and nestin (p = 0.03) than benign nevi." (PMID 27429260, 2014). "Tissue microarrays of normal tissue and 226 melanocytic lesions (71 banal nevi, 71 in situ and invasive melanomas and 84 metastatic melanomas) were investigated for immunohistochemical expression of CD166, CD133, and nestin." (PMID 27429260, 2014).
oral cancer (5 papers, 2012 to 2024). "As a whole, our analysis showed an increase in the number of nestin-GFP/NG2-DsRed pericytes in carcinogen-induced oral cancer lesions." (PMID 37015965, 2023). "A gradually increased expression of nestin was found along the transformation stages of oral cancer." (PMID 33805026, 2021). "Ravindran and Devaraj studied the expression pattern and prognostic significance of two neural stem cell markers, nestin and musashi-1, in oral cancer." (PMID 33805026, 2021). "Association with higher stage and poor differentiated status of oral carcinomas was identified with nestin or musashi-1 positive lesions." (PMID 33805026, 2021). "At a minimum, our study data support the notion that nestin plays a brief but pivotal role in oral carcinogenesis and may be a valuable marker for neoangiogenesis in oral cancer." (PMID 31675305, 2019).
pituitary adenomas (5 papers, 2014 to 2023). "The hPASCs were successfully isolated and cultured from gonadotrophic pituitary adenoma in vitro, which were identified as positive for generic stem cell markers (Sox2, Oct4, Nestin and CD133) via immunohistochemical staining." (PMID 36750863, 2023). "ERα shRNA-knockdown was found to exacerbate the bromocriptine-induced inhibition of tumorsphere formation in CD133+/nestin+ pituitary adenoma stem-like cells." (PMID 33173437, 2020). "The same protocol was used in the present study, where CD133+/nestin+ pituitary adenoma stem-like cells were isolated and transiently transfected with pPLK/GFP+Puro-ERα or the corresponding control shRNA." (PMID 33173437, 2020). "CD133+/nestin+ HPA cells form spheres and differentiate, suggesting the differentiation capacity and high tumorigenic ability of CD133+/nestin+ pituitary adenoma stem-like cells." (PMID 33173437, 2020). "Furthermore, ERα shRNA-knockdown exacerbated the bromocriptine-induced inhibition of cellular proliferation and tumorsphere formation in primary cultured HPA cells and their counterpart CD133+/nestin+ pituitary adenoma stem-like cells." (PMID 33173437, 2020). "Moreover, nestin expression was detected in endothelial cells of pituitary adenomas and in a carcinoma sample." (PMID 25505910, 2014). "We found that nestin expression was evidenced only in the adenomatous pituitaries and correlated positively with the percentage of small vessels and negatively with years since the first diagnosis of pituitary adenoma." (PMID 25505910, 2014). "In a previous study, primary pituitary adenoma and stem-like cells were isolated using CD133 and Nestin magnetic beads 20,28." (PMID 33173437, 2020). "Immunohistochemical staining was commonly used for verification of tumor stem cells in pituitary adenoma; four generic markers, namely Sox2, CD133, Nestin and Oct4 were selected and showed immunopositivity in the cultured hPASCs, thus validating the properties of their stemness." (PMID 36750863, 2023).
schizophrenia (5 papers, 2019 to 2022). A major psychotic disorder characterized by abnormalities in the perception or expression of reality. "At the end of each culture period, NPCs in both control and schizophrenia-derived cells stained positive for neural progenitor markers such as nestin and SOX2 (SRY-Box 2)." (PMID 36451159, 2022). "There are only a few reports indicating a relationship between schizophrenia pathogenesis and nestin concentration." (PMID 35408792, 2022). "In offspring of pregnant C57Bl/6 mice injected with polyriboinosinicpolyribocytidylic acid (poly I:C, maternal immune activation model), which go on to develop a schizophrenia-like phenotype in adulthood, nestin is increased relative to control." (PMID 35408792, 2022). "The hippocampus was selected as the region of interest for this because the majority of nestin-expressing NSCs are found in the hippocampus; this brain area has also been shown to be involved in neurogenesis-related abnormalities in schizophrenia patients." (PMID 35408792, 2022). "We hypothesized that schizophrenia pathogenesis involves nestin downregulation; however, few studies have related nestin to schizophrenia." (PMID 35408792, 2022). "Nestin concentration was reduced in cells obtained from patients with schizophrenia." (PMID 35408792, 2022). "We hypothesize that one of the aspects of schizophrenia pathogenesis could be the downregulation of nestin expression and that clozapine, the prototypical atypical antipsychotic, could reverse this process." (PMID 35408792, 2022). "While we chose to use a pharmacological model of schizophrenia, we recognize that using a neurodevelopmental model may provide additional insights given the involvement of nestin in neurodevelopment and the early stages of progenitor cells differentiating into their mature cell types." (PMID 35408792, 2022). "We assessed nestin protein concentration, prepulse inhibition (PPI), and social interaction in the MK-801 model of schizophrenia, with or without antipsychotic (clozapine) treatment." (PMID 35408792, 2022).
teratoma (5 papers, 2014 to 2025). A non-seminomatous germ cell tumor characterized by the presence of various tissues which correspond to the different germinal layers (endoderm, mesoderm, and ectoderm). "Immunohistochemical analysis also revealed that NESTIN was largely absent from primitive neuroepithelia tubules in Strap–/– teratoma compared to that in WT, characterizing an immature neural tissue lacking neural progenitors." (PMID 33230114, 2020).
triple-negative breast carcinoma (5 papers, 2014 to 2022). An invasive breast carcinoma which is negative for expression of estrogen receptor (ER), progesterone receptor (PR), and human epidermal growth factor receptor 2 (HER2). "In the present study, we first characterized Nestin expression in 150 tumor specimens from patients with triple-negative breast cancer, and analyzed the potential association between levels of Nestin expression and the survival of patients." (PMID 25056574, 2014). "Nestin expression was significantly associated with poor survival in patients with triple-negative breast cancer (P = 0.01)." (PMID 25056574, 2014). "Importantly, Nestin expression was significantly associated with poor survival in patients with triple-negative breast cancer." (PMID 25056574, 2014). "Nestin was preferentially expressed in invasive ductal carcinoma, triple-negative breast cancer and basal-like subtypes." (PMID 32467665, 2020). "In this study, we examined Nestin expression in 150 specimens of triple-negative breast cancers, and found that 41 (27.33%) out of them were positive for anti-Nestin staining." (PMID 25056574, 2014). "Survival analysis indicated that the survival of patients with Nestin+ triple-negative breast cancer was significantly reduced when compared with Nestin− triple-negative breast cancer (P = 0.01)." (PMID 25056574, 2014). "Although this study examined a relatively small number of breast tumor samples, our findings extended previous observations to confirm the importance of Nestin expression in the prognosis of triple-negative breast cancer." (PMID 25056574, 2014). "Nestin expression in 150 triple-negative breast cancer specimens were examined by immunohistochemistry." (PMID 25056574, 2014). "We isolated CD44+CD24− CSC from 26 triple-negative breast cancer tissues to generate Nestin-overexpressing (Nestin+), Nestin-silencing (Nestin-si), and control (Nestin-c) CSC." (PMID 25056574, 2014). "Nestin (NES) is an intermediate filament protein expressed by cancer cells, in particular by cancer stem cells and is associated with poor prognosis in patients with triple negative breast cancer." (PMID 35821197, 2022). "Our data therefore suggest that Nestin may be a potential therapeutic target for triple-negative breast cancer." (PMID 25056574, 2014). "Therefore, Nestin may be a therapeutic target and prognostic biomarker for triple-negative breast cancer." (PMID 25056574, 2014). "More importantly, nine studies with 4335 patients compared the nestin expression between triple negative breast cancer (TNBC) and non-triple negative breast cancer." (PMID 32467665, 2020). "To further understand the role of Nestin in the development and progression of triple-negative breast cancer, we characterized the levels of Nestin expression in 150 specimens from patients with triple-negative breast cancer by immunohistochemistry." (PMID 25056574, 2014). "Our findings suggest that Nestin may enhance the proliferation and survival of breast CSC, contributing to the progression of triple-negative breast cancer." (PMID 25056574, 2014). "Taken together, the rapid formation of mammospheres in vitro and the efficient induction of solid tumors in vivo clearly demonstrated that higher levels of Nestin expression enhanced the tumorigenicity of CSC, which may contribute to the progression and metastasis of triple-negative breast cancer." (PMID 25056574, 2014).
atherosclerosis (4 papers, 2016 to 2022). A disease characterized by the build-up of fatty material and calcium deposition in the arterial wall resulting in partial or complete occlusion of the arterial lumen. "Here, we used a systems-based approach, combining RNAseq analysis and protein profiling, to identify nestin as a highly EC-enriched intermediate filament in the human adult, and to characterise its expression in malignancy and atherosclerosis." (PMID 30279450, 2018). "The cellular redistribution of nestin under flow and the effects of nestin knockdown on wound healing and proliferation led us to investigate nestin expression in the context of atherosclerosis." (PMID 30279450, 2018). "The present study demonstrates that nestin+ stromal cells direct inflammatory cell migration in different compartments as a critical initial step in atherosclerosis." (PMID 27586429, 2016). "Altogether, this study highlights the relevance of nestin+ cells in directing inflammatory cell migration during the early stages of atherosclerosis, possibly applicable to other chronic inflammatory diseases." (PMID 27586429, 2016). "First, we studied the contribution of nestin+ stromal cells and endothelial cells to BM egress of inflammatory cells in atherosclerosis." (PMID 27586429, 2016). "A likely explanation is that the most relevant source of Mcp1 in atherosclerosis is the nestin+ cell population residing in the aorta." (PMID 27586429, 2016). "Here, the authors show that nestin-producing stromal cells direct inflammatory cell migration in atherosclerosis, and that stromal Mcp1 is crucial in this process." (PMID 27586429, 2016). "Our results in atherosclerosis are consistent with the overall chemotactic role of Mcp1 in various compartments and point towards a gatekeeper function of this chemokine expressed by nestin+ cells." (PMID 27586429, 2016). "Therefore, nestin expression marks cells that regulate inflammatory cell migration during atherosclerosis." (PMID 27586429, 2016). "However, it remains unknown whether nestin+ cells regulate inflammatory cells in chronic inflammatory diseases, such as atherosclerosis." (PMID 27586429, 2016). "The role of nestin in human atherosclerosis is not well studied, although the disease-associated modified shear stress is well known to affect several processes in which we have here demonstrated a functional role of nestin, such as cytoskeletal rearrangement, wound repair and proliferation." (PMID 30279450, 2018).
breast tumor (4 papers, 2011 to 2024). "Brain metastases as the first site of distant recurrence were associated most frequently with the basal subtype and primary tumor expression of nestin, prominin-1, or CK-5, and, on the other hand, they were rare when the breast tumor expressed ER or PgR." (PMID 21914172, 2011). "In this regard, a histological co-expression of MT1 with nestin—a stem cell marker—has been described in human breast tumor tissue, which implies that MT1 would also be expressed and would be relevant in highly malignant neoplasms that are negatively correlated with ERα." (PMID 38672378, 2024).
Gliosis (4 papers, 2017 to 2024). Gliosis is the focal proliferation of glial cells in the central nervous system. "We first confirmed that cuprizone induced similar levels of demyelination and gliosis in the Myrf-Het;Nestin-tdT and the Myrf-cKO;Nestin-tdT mice based on MBP and Eriochrome Cyanine stainings, and on GFAP and Iba1 stainings." (PMID 36779010, 2023). "Gliosis is accompanied by the higher generation of the intermediate filament including GFAP, nestin, and vimentin, which leads to greater and more highly condensed glial processes and fibers." (PMID 38630361, 2024). "Gliosis is accompanied by the emergence of reactive astrocytes and can be determined not only by an increased number of GFAP positive (GFAP+) cells but also by the upregulation of other IFs like vimentin and nestin, as well as a rise of proliferating Ki67 positive cells." (PMID 28841900, 2017).
Hypertension (4 papers, 2018 to 2025). The presence of chronic increased pressure in the systemic arterial system. "The only published rat model of hypertension describing nestin positivity in cardiomyocytes concerns the suprarenal abdominal aorta constriction (SAC)." (PMID 36690826, 2024). "Lastly, vascular remodeling secondary to hypertension was attributed in part to the increased density of nestin(+)-vascular smooth muscle cells the re-entered the cell cycle." (PMID 29492403, 2018).
Insulin resistance (4 papers, 2008 to 2025). Increased resistance towards insulin, that is, diminished effectiveness of insulin in reducing blood glucose levels. "This was supported by the fact that in Nestin (+) NSCs, the differentiation fate was affected by streptozotocin, a compound causing insulin resistance." (PMID 33157254, 2021). "We conclude that although Nestin-CRE mice display a significant metabolic phenotype, ablation of PI3Kγ in neurons protects mice from HFD-induced insulin resistance." (PMID 39811649, 2025).
multiple myeloma (4 papers, 2012 to 2025). "A variety of clinical drugs affect the expression of nestin through signal pathways, and then affect the proliferation of CSCs and myeloma." (PMID 40799240, 2025). "The presence of another component of the BM, nestin+ mesenchymal cells, was also examined in myeloma." (PMID 22347385, 2012).